CD33 (CD33 molecule)
Diseases named in the same sentence as CD33 in open-access papers (continued):
Sharing a sentence is not in itself a finding about the gene and the disease.
prostate carcinoma (6 papers, 2006 to 2024). A carcinoma that arises from epithelial cells of the prostate gland. "Previous research had indicated that increased levels of CD33 might have contributed to an elevated risk of prostate cancer." (PMID 38888513, 2024). "This suggested that tumor cells could have evaded immune system attacks by interacting with Siglecs expressed on CD33-bearing cells, thus contributing to an increased risk of prostate cancer." (PMID 38888513, 2024). "The modified scFvs recognize either prostate stem cell antigen (PSCA), a prostate cancer (PCa) specific antigen or CD33, a cell surface glycoprotein specific for hematopoietic cells of myeloid origin." (PMID 24699869, 2014). "Our findings reveal expression of ST6GAL1 alters sialoglycan patterns in prostate cancer cells, and in line with the literature, we find ST6GAL1 specifically regulates sialoglycans that engage Siglec-2 (CD22) and Siglec 3 (CD33)." (PMID 38772281, 2024). "The data presented reveals ST6GAL1 controls the expression sialoglycans on prostate cancer cells including ligands that could engage Siglec-2 (CD22) and Siglec-3 (CD33) on immune cells." (PMID 38772281, 2024). "Therefore, the abnormal expression of CD33 and LGALS3BP might have collaboratively facilitated the development of prostate cancer and immune evasion." (PMID 38888513, 2024).
sarcoma (6 papers, 2011 to 2021). A usually aggressive malignant neoplasm of the soft tissue or bone. "Relationship between CD68, CD163 and CD33 density and patient characteristics of fibroblastic sarcomas." (PMID 34257571, 2021). "In summary, this study implies that HMGB1 released by tumor cells and vascular endothelial cells may modulate the infiltration, polarization and function of TAMs and CD33-positive myeloid cells, thereby contributing to the progression of fibroblastic sarcomas." (PMID 34257571, 2021). "In fibroblastic sarcomas, the total score and the cytoplasm-staining score of HMGB1 were positively correlated with CD68, CD163 and CD33 density, indicating that HMGB1 may act on M2-polarized TAMs and CD33-positive myeloid cells in fibroblastic sarcomas and contribute to disease progression." (PMID 34257571, 2021). "Correlation analysis revealed that the density of CD68, CD163 and CD33 was not only positively correlated with the total score of HMGB1, but also with the cytoplasm-staining score of HMGB1 in fibroblastic sarcomas." (PMID 34257571, 2021). "The correlations between the expression of ST2 and CD4, CD8A, and CD33, and between IL-33 and CD8A and CD45RO were then validated by analysis using GSE2719 or GSE 967 GEO datasets of sarcoma." (PMID 29896199, 2018). "Compared with TAMs, the density of CD33-positive myeloid cells was much lower in fibroblastic sarcoma and not significantly related to disease progression." (PMID 34257571, 2021). "Histiocytic sarcoma cells are derived from bone marrow monocyte precursors, expresses monocyte-macrophage antigens (CD163, CD68, and lysozyme) and lack expression of myeloid antigens such as CD33, CD13 and MPO." (PMID 29463311, 2018).
anemia (5 papers, 2010 to 2025). A reduction in the number of red blood cells, the amount of hemoglobin, and/or the volume of packed red blood cells. "Although we did not observe a significant elimination of hematopoietic stem cells in vitro, CAR T-cells targeting CD33 could exacerbate anemia and thrombocytopenia in virtue of CD33 expression on these hematopoietic progenitors, as previously observed in preclinical models in vitro, or in vivo." (PMID 27907031, 2016). "Patients with sJIA and anemia had a significantly larger proportion of circulating CD34+, CD34+CD33-, and CD34+CD33+ cells than did individuals with non-sJIA with or without anemia." (PMID 20576155, 2010).
chronic myeloid leukemia (5 papers, 2016 to 2023). "Moreover, the cells with positive staining of CD13 or CD33, the surface markers of K562 cells, as well as the mRNA levels of bcr/abl fusion gene, a marker of chronic myeloid leukemia, in peripheral blood and bone marrow of IVM plus ADR-treated mice were lower than that in the ADR alone-treated mice." (PMID 31215501, 2019). "Previous studies have shown that the crosslinking of CD33 by monoclonal antibody induces apoptosis in AML cells and inhibits the in vitro proliferation of both normal myeloid cells and chronic myeloid leukemia." (PMID 37081561, 2023).
myeloid sarcoma (5 papers, 2018 to 2024). A tumor mass composed of myeloblasts or immature myeloid cells. "In AML/myeloid sarcoma, MPO, CD117, CD33, CD34, and TdT are positively expressed but B- and T-lineage markers are negative." (PMID 39559598, 2024). "At day 28, mice treated exclusively with CD33 and CD117 Db-FM experienced the occurrence of extramedullary manifestations as myeloid sarcomas." (PMID 39294295, 2024). "A concurrent lymph node biopsy demonstrated necrosis and surrounding CD43- and CD33-positive myeloid cells that were highly suggestive of the involvement of the lymph node by myeloid sarcoma (unfortunately flow cytometry was not performed)." (PMID 30559310, 2018). "Flow cytometry showed an immature cell population (CD45 dim) that was negative for CD34, CD56, CD117, and MPO; strongly positive for CD4; and variably positive for CD10, CD33, HLA‐DR, CD68, CD123, and E‐cadherin, consistent with myeloid sarcoma (MS)." (PMID 31788302, 2019).
chronic myelomonocytic leukemia (4 papers, 2018 to 2023). A myelodysplastic/myeloproliferative neoplasm which is characterized by persistent monocytosis, absence of a Philadelphia chromosome and BCR/ABL fusion gene, fewer than 20 percent blasts in the bone marrow and blood, myelodysplasia, and absence of PDGFRA or PDGFRB rearrangement. "PRGN-3006, a CD33-directed CAR-T with IL-15 membrane bound, was tested in 20 R/R AML, 1 chronic myelomonocytic leukemia (CMML) with ≥5% blasts, and 3 high-risk MDS without (cohort 1) or with lymphodepletion (fludarabine 30 mg/m2 and cyclophosphamide 500 mg/m2 days −5 to −3; cohort 2)." (PMID 37892958, 2023).
HIV-1 infection (4 papers, 2014 to 2025). The type species of lentivirus and the etiologic agent of acquired immunodeficiency syndrome (AIDS). "The clinical relevance of these findings is further supported by our observation that anti-CD33 monoclonal antibody in vitro blocked virus replication and integration, thus identifying CD33 as a potentially therapeutic target in HIV-1 infection." (PMID 37506557, 2023). "Higher CD33/Siglec-3 plasma levels were also observed in individuals with high viral loads in an unrelated cohort with untreated HIV-1 infection." (PMID 37506557, 2023). "Here we identify plasma CD33/Siglec-3 levels as a biomarker associated with HIV-1 control during the clinical BCN02 trial but also in a large cohort of individuals with chronic, untreated HIV-1 infection." (PMID 37506557, 2023). "Given this evidence, it is tempting to propose that anti-CD33 mAb could be employed in HIV-1 infection, with a potential dual beneficial effects of reducing HIV-1 replication and improving HIV-1-associated neurocognitive deficits." (PMID 37506557, 2023). "Therefore, further exploring the role and mechanism of CD33 on Mo MDSC in the establishment of HIV-1 infection may be beneficial to the prevention and control of HIV-1." (PMID 40603539, 2025). "As cell surface CD33 is an interferon inducible factor, higher viral burden could induce its production, and in more extreme situation, shedding of CD33 into the plasma, as has been described for another member of the Siglec family (Siglec-7) in uncontrolled HIV-1 infection." (PMID 37506557, 2023).
neuroblastoma (4 papers, 2013 to 2023). Neuroblastoma (NB) is the most common solid, extracranial childhood tumor. "Furthermore, high-risk neuroblastoma exhibited higher levels of CD33+CD11b+HLA-DR− MDSCs (M-MDSC) than low-risk neuroblastoma." (PMID 38087370, 2023). "We detected the significantly correlated expression of M2 TAMs marker genes (CD163, CD204, CD206) and M-MDSC marker genes (CD11B, CD14, CD33) in the high-risk neuroblastoma examined, suggesting that the various numbers of M2 TAMs and MDSCs are present in the high-risk neuroblastoma TME." (PMID 33968044, 2021). "Interestingly, co-culture experiments demonstrated that endothelial cells down-regulated adhesion receptor CD33 upon interaction with neuroblastoma cells, thus impairing neutrophil adhesion and extravasation." (PMID 38087370, 2023). "Furthermore, we found that high-risk primary neuroblastoma tumors contain CD68+ tumor-associated monocytes/macrophages (TAMs) producing IL-6 and that bone marrows with neuroblastoma metastases include CD33+ CD14+ monocytic cells, which also express IL-6." (PMID 23982484, 2013). "Similarly, more CD33+ myeloid cells infiltrated a melanoma PDX in humanized NSG-SGM3 compared to NSG mice, and a neuroblastoma PDX MISTRG humanized mouse model recapitulated the lack of activated human NK cells observed in neuroblastoma patients." (PMID 37296949, 2023).
Obesity (4 papers, 2020 to 2024). Accumulation of substantial excess body fat. "Previous research indicated that the frequency of CD33 + cells in blood, as a subset of myeloid‐derived suppressor cells, was significantly higher in obese subjects compared to nonobese individuals, providing some evidence for a potential modifying effect of obesity." (PMID 32207560, 2020).
schizophrenia (4 papers, 2021 to 2025). A major psychotic disorder characterized by abnormalities in the perception or expression of reality. "In particular, we found negative factors related to AD (including short sleep duration, CAD, schizophrenia, elevated LDL-C and CD33 protein levels, short telomeres, and high expression of CR1), which are crucial for setting inclusion and exclusion criteria in future population studies." (PMID 40082927, 2025). "While no direct link between schizophrenia and the CD33-related SIGLECs has been described so far, patient-specific polymorphisms in the SIGLEC4/MAG gene expressed in oligodendrocytes have been significantly associated with the disease." (PMID 38529039, 2024).
systemic lupus erythematosus (4 papers, 2017 to 2022). An autoimmune multi-organ disease typically associated with vasculopathy and autoantibody production. "Consistent with defective self-tolerance, CD33/LAIR-1 expression is reduced in systemic lupus erythematosus (SLE) myelomonocytes." (PMID 28325905, 2017). "It has been reported that LDNs expressing CD15+CD11b+CD33+HLA‐DR− are activated neutrophils that undergo degranulation and a series of inflammatory processes in multiple autoimmune diseases such as systemic lupus erythematosus (SLE), psoriasis, and arthritis." (PMID 34894104, 2022).
T-cell ALL (4 papers, 2018 to 2024). "In T-cell ALL, the most frequent aberrant markers were CD10 (44.3%), CD13 (36.5%), CD33 (25.4%) and CD117 (19%)." (PMID 36629681, 2023). "It is also noteworthy that only markers of myeloid origin were expressed as aberrant phenotype in T-cell ALL (CD13, CD33 and HLA-DR) while common T-cell markers i.e. CD3 and CD7 were aberrantly expressed in 3% cases of B-cell ALL/ TAg+ B-ALL." (PMID 29805426, 2018).
acute monocytic leukemia (3 papers, 2012 to 2023). Acute monoblastic leukemia (AML-M5), is one of the most common subtypes of acute myeloid leukemia (AML) that is either comprised of more than 80% of monoblasts (AML-M5a) or 30-80% monoblasts with (pro)monocytic differentiation (AML-M5b). "After transduction with lentiviral particles coding for the different CAR constructs Jurkat-TPR was cocultured with MOLM-13 cells, an AML cell line expressing CD33 established from the peripheral blood of an acute monocytic leukemia relapsed patient." (PMID 37795087, 2023). "Immunophenotypic analysis of the bone marrow showed expression of CD11b, CD13, CD14, CD15, CD33, CD34, CD45 and human leukocyte antigen-DR, findings compatible with the diagnosis of acute monoblastic leukemia (French-American-British classification M5a)." (PMID 22339850, 2012).
B-cell acute lymphoblastic leukemia (3 papers, 2020 to 2024). A neoplasm of lymphoblasts committed to the B-cell lineage, typically composed of small to medium-sized blast cells. "In B-cell acute lymphoblastic leukemia, the most frequent aberrant markers were CD66c, CD13 and CD33." (PMID 36629681, 2023).
chronic hepatitis B (3 papers, 2024 to 2025). "Moreover, CD33 is associated with an increased risk of HCC among chronic hepatitis B-infected individuals." (PMID 40551711, 2025). "By quantifying the frequency of cells expressing CD33 and HBV surface antigen (HBsAg) using peripheral blood mononuclear cells isolated from patients with chronic hepatitis B, 56.5% of CD33-positive cells were found to be bound to HBsAg and almost all HBsAg-positive cells were bound to CD33." (PMID 37962454, 2024).
colorectal adenocarcinoma (3 papers, 2015 to 2021). The most common type of colorectal carcinoma. "The colorectal adenocarcinomas examined in this study seem to directly induce suppression of the host immune response by the overexpression of PD-L1 and CD33 molecules." (PMID 33625532, 2021). "A higher number of cells expressing IL-2Rα, PD-L1, CD33 and CD14 were found in colorectal adenocarcinomas than in controls." (PMID 33625532, 2021).
head and neck cancer (3 papers, 2011 to 2024). A primary or metastatic malignant neoplasm affecting the head and neck. "Of over 100 tumor cell lines examined, 45 generated canonical CD33+HLA-DRlowLineage- MDSC, with high frequency of induction by cervical, ovarian, colorectal, renal cell, and head and neck carcinoma cell lines." (PMID 21658270, 2011).
kidney cancer (3 papers, 2019 to 2023). Primary or metastatic malignant neoplasm involving the kidney. "The mechanism of this drug led to investigate of what role it could have in other types of neoplasms such as kidney cancer, where CD33+ MDSCs were identified in blood samples, which were found in a higher concentration compared to healthy people." (PMID 37396098, 2023).
lung adenocarcinoma (3 papers, 2017 to 2022). A carcinoma that arises from the lung and is characterized by the presence of malignant glandular epithelial cells. "High CD33 expression was associated with a significantly improved survival rate in patients with lung adenocarcinoma from the TCGA dataset." (PMID 35493454, 2022). "Examination of lung adenocarcinoma data from the TCGA cohort showed that high CD33 expression was associated with increased survival." (PMID 35493454, 2022). "We addressed this by testing associations between CD33 expression and survival in patients with either lung adenocarcinoma and lung squamous cell carcinoma." (PMID 35493454, 2022). "Data from one patient with lung adenocarcinomas indicated an increased number of myeloid-derived suppressor cells (MDSCs; CD206+/CD33+/HLA-DR-) and double negative (CD4-/CD8-) T cells infiltrating this tumor when compared to the corresponding numbers of these cells in the blood." (PMID 28977993, 2017).
meningioma (3 papers, 2013 to 2023). A generally slow growing tumor attached to the dura mater. "CD45+ inflammatory cells that infiltrated meningiomas mainly included tissue macrophages (TiMa) with an HLA-DR+CD14+CD45+CD68+CD16−/+CD33−/+ phenotype and a high phagocytic/endocytic activity, together with a smaller population of cytotoxic lymphocytes, mostly CD8+ T cells and NK-cells." (PMID 24098347, 2013). "In contrast, there was a modest but significant increase in relative expression of myeloid markers (CD14, CD33 and CD74) in NF2 meningiomas, suggesting higher infiltration of NF2 tumors by myeloid cells." (PMID 36937440, 2023). "In two resections of atypical meningioma, we found that both CD45+CD33+ tumor infiltrating myeloid cells and the CD45− non-immune cells which include meningioma cells express PD-L1." (PMID 25609200, 2015). "In addition, TiMa from meningiomas with isolated monosomy 22/del(22q) also displayed a higher percentage of CD16+ cells vs tumors with complex karyotypes (p = 0.004); despite not statistically significant, higher percentages of CD33+ cells were also associated with −22/22q− cases." (PMID 24098347, 2013).
nasopharyngeal carcinoma (3 papers, 2015 to 2023). A carcinoma arising from the nasopharyngeal epithelium. "We here report that Gal-9 expression in nasopharyngeal carcinoma (NPC) cells enhances the generation of MDSCs (CD33+CD11b+HLA-DR−) from CD33+ bystander cells." (PMID 32632113, 2020). "The ectopic STING expression negatively correlates with tumor-infiltrating CD33+ cells and decreases the percent of nasopharyngeal carcinoma (NPC)-induced HLA-DR−CD11b+CD33+ MDSCs." (PMID 37380989, 2023).
osteoporosis (3 papers, 2021 to 2025). A condition of reduced bone mass, with decreased cortical thickness and a decrease in the number and size of the trabeculae of cancellous bone (but normal chemical composition), resulting in increased fracture incidence. "MR results show that CD45 on CD33dim HLA DR+ CD11b-, CD45 on Mo MDSC, and CD33- HLA DR+ AC were protective factors against osteoporosis, and all three were associated with Myeloid cells." (PMID 39086903, 2024). "The OR of CD33- HLA DR+AC (Myeloid cell panel) risk on Osteoporosis was estimated to be 0.9996 (95% CI = 0.9993~0.9999, P = 0.038)." (PMID 39086903, 2024). "The low expression of CD11b and CD33 in myeloid cells may limit their cell adhesion and migration functions, suggesting a negative causal effect on osteoporosis, which is enlightening." (PMID 39086903, 2024). "A 5-gene combination (CCR1, CD33, HCK, LILRB2 and CYBB) was established as an optimal and effective biomarker for osteoporosis using SVM with feature selection and classification procedures." (PMID 34622712, 2021).
Splenomegaly (3 papers, 2015 to 2020). Abnormal increased size of the spleen. "More importantly, c-MYChighMYCBP2low patients showed higher median WBC counts, higher percentage of CD34(+) and CD33(+) cells, higher rate of splenomegaly, liver infiltration, increased LDH, and lower CR rate compared with that of c-MYClowMYCBP2high patients." (PMID 26517351, 2015). "Patients with high c-MYC expression and/or low MYCBP2 expression had higher WBC counts and a higher percentage of CD34+ or CD33+ cells, as well as splenomegaly, liver infiltration, higher BM blasts, and lower CR rate." (PMID 26517351, 2015). "Engrafted CMML#1-MN1 cells had a myeloid phenotype expressing CD33, CD38, and CD123, but lacked expression of lymphoid markers CD3 and CD19, and developed splenomegaly." (PMID 32576961, 2020).
acquired immunodeficiency syndrome (2 papers, 2015 to 2022). "Compared with normal neutrophils, LDNs in patients with acquired immunodeficiency syndrome expressed increased levels of CD15, CD33, CD66b, and decreased levels of CD62L, CD80, CD114, and CXCR417." (PMID 35027618, 2022).
allergic rhinitis (2 papers, 2020 to 2024). Inflammation of the nasal mucous membranes caused by an IgE-mediated response to external allergens. "For instance, a study conducted by Shiteng Duan in 2019 demonstrated that CD33 recruitment can attenuate IgE-mediated allergic reactions and desensitize mast cells to allergens, thereby slowing down the progression of allergic rhinitis." (PMID 39399526, 2024). "In the UKB cohort, CD33 variant rs3865444 had nominal association with asthma (p = 2.84 x 10−4), while CD2AP variant rs9349407 had nominal association with UC (p = 0.0004) and PICALM variant rs3851179 had nominal association with hay fever or allergic rhinitis (p = 4.42 x 10−4)." (PMID 33152005, 2020).